CD36 (CD36 molecule (CD36 blood group))
Diseases named in the same sentence as CD36 in open-access papers (continued):
Sharing a sentence is not in itself a finding about the gene and the disease.
cancer (continued). "Indeed, it has been recently shown that cancer cells expressing high levels of the receptor CD36 and lipid metabolism genes, are more likely to initiate metastasis in the presence of an excess of dietary fat." (PMID 29167646, 2017). "However, CAV1 (p = 8.3 × 10−6) and CD36 (p = 0.01) were both significantly amplified across all cancers according to the genome-wide GISTIC analysis." (PMID 26725848, 2016). "While it functions as a fatty acid transporter, CD36 is also involved in collagen adhesion and, therefore, less CD36 may reduce cell adhesion, providing cancer cells with a higher metastatic potential." (PMID 25866768, 2015). "These compounds have shown potential for treatment of cancer suggesting that targeting CD36 or HRG could present effective alternative approaches to enhance or inhibit TSR action." (PMID 22808089, 2012). "Targeting CD36 in macrophages and cancer cells could modulate disease development and progression." (PMID 40563926, 2025). "Moreover, recent studies have revealed that CD36 contributes to the tumorigenesis and development of multiple cancer types by reprogramming the metabolism of glucose and fatty acid, providing new insights for developing potential therapeutic target and prognostic biomarker in the clinical setting." (PMID 40436827, 2025). "Moreover, it was proved that cancers with a higher abundance of CD36 exhibit unfavorable course." (PMID 40076482, 2025). "However, it could be considered that CD36 can transport FA inside and outside the cells, and it cannot be excluded that normal mammary gland tissue cells also supply cancer cells with VLCFA." (PMID 40759952, 2025). "Furthermore, we investigate whether blocking the interaction between CD36 and PS will prevent fusion between monocytes and cancer cells." (PMID 39752516, 2025). "Notably, CD36-mediated uptake of oxidized LDL (ox-LDL) triggers a pathway involving Nogo-B and CEBPβ expression, ultimately reprogramming ox-LDL metabolism and driving cancer development in NAFLD-associated HCC." (PMID 38833109, 2024). "For instance, evidence suggests that CD36 may contribute to the metastatic process in several cancers, while MYD88 mutations have been implicated in the dysregulation of immune responses in cancer pathogenesis." (PMID 38742843, 2024). "However, previous research has established CD36 as a pivotal biomarker for cancer, showing a negative association with patients’ outcomes." (PMID 39691192, 2024). "In addition, by promoting metabolic rewiring in cancer cells, CD36 may induce resistance to chemotherapy or targeted therapy, suggesting potential therapeutic strategies." (PMID 39624081, 2024). "Importantly, a high CD36 expression level has also been shown to correlate with worse prognosis in the brain, cervical, colorectal, gastric, pancreatic, and prostate cancers." (PMID 37371076, 2023). "Therefore, we studied whether MMP9, MMP12, FABP4, and CD36 genes are correlated with poor prognosis in various cancers." (PMID 37978381, 2023). "Given that PPARα regulates the expression of CD36 in fatty acid metabolism, it may be possible in the future to utilize PPARα to inhibit CD36 expression or block its function, thereby providing a potential therapeutic approach for inhibiting cancer cell metastasis." (PMID 38004166, 2023). "Since CSCs are subpopulations of cancer cells that exhibit a self-renewal capability and resistance to chemotherapies, targeting CD36 may offer a strategy to target these notoriously difficult-to-eliminate populations responsible for therapy relapses among patients." (PMID 37371076, 2023). "Further, a study of over 2500 cases of different types of cancers stratified in metastatic versus primary tumors revealed that the CD36 gene was frequently amplified in metastatic groups and, similarly, poor survival rates correlate with CD36 high-copy numbers." (PMID 36980201, 2023). "Many of these trends could be further enhanced via CD36 overexpression in cancer cells." (PMID 37371076, 2023).
cancer (continued). "As CD36 expression in cancer cells drives stem cell-like traits, and promotes drug resistance and metastatic potential of CSCs, PKD1-mediated CD36 expression might also play an important role in metastatic progression of pNETs, very likely via CD36-mediated fatty acid metabolism." (PMID 36497140, 2022). "Thus, CD36 has been pointed as a potential therapeutic target in cancer." (PMID 36568966, 2022). "Thus, CD36 is currently studied as an emerging therapeutic target in cancer." (PMID 36568966, 2022). "In the liver, AIM is taken up by cells via CD36 where it demonstrates lipolytic activity in normal cells; however, in cancer cells, cellular uptake is suppressed, and AIM accumulates on the cell surface, activating complement proteins and causing subsequent cancer cell death." (PMID 34981443, 2022). "Thus, it is tempting to speculate that CD1d-dependent regulation of CD36 functions in cancer cells could contribute to modulate their survival, proliferation and/or metastatic potential and consequently influence disease progression and response to treatment." (PMID 36344546, 2022). "In this regard, CD36 may serve as a promising anti-cancer target." (PMID 39872079, 2022). "This might facilitate the ferroptosis of malignant tumors overexpressing CD36." (PMID 33801564, 2021). "Therefore, drugs targeting CD36 have potential to target cancer, and we may improve the prognosis of cancers by reducing the intake of lipids in the diet." (PMID 34603046, 2021). "These contrasting reports on CD36 function may indicate its context-specific role in cancer." (PMID 34561446, 2021). "Thus, a large number of FAs’ molecules via CD36 supports cancer cell proliferation." (PMID 32781778, 2020). "Therefore, CD36 might represent a potential target for the prevention and therapy of cancer metastasis." (PMID 31410189, 2019). "In addition to metabolic diseases, CD36 can be involved in the occurrence of cancer." (PMID 31379931, 2019). "Furthermore, the expression of CD36 by plasmid transfection could rescue the invasion ability of CD36-knockout cancer cells, but the expression of CD36 with S468A, T470A or S468A/T470A mutations could not." (PMID 31410220, 2019). "Therefore, CD36 is now regarded as a potential biomarker and therapeutic target for cancer." (PMID 31410189, 2019). "Interestingly, CD36 has been shown to be involved in cancer metastasis." (PMID 31766495, 2019). "Treatment of these cells with sulfo-N-succinyl oleate (SSO), an inhibitor of CD36 fatty acid translocase, reduced the number of lipid droplets in cancer cells, suggesting that the increase of lipid droplets following incubation with fatty acids may have been due to the direct uptake of fatty acids." (PMID 28407685, 2017). "This inconsistency between cancer types may be explained by the multifunctionality of CD36." (PMID 25866768, 2015). "Among them, MMP9, important in extracellular matrix degradation, is up-regulated in three of the seven cancers, and CD36, which may function in cell adhesion, is down-regulated in three of the seven cancers; both of these changes are consistent with a role of the gene products in metastasis." (PMID 21060876, 2010). "To evaluate CD36's role in cancer-related pathways, we performed an extensive GSEA analysis of 33 cancers." (PMID 41550652, 2025). "Simultaneously, cancer cells exploit exogenous lipid sources through dietary uptake, with cluster of differentiation 36 (CD36) functioning as a major fatty acid translocase." (PMID 40901479, 2025). "The bar charts show the total alteration frequency of six hub genes (CD36, CXCL12, CXCR4, CYBB, ITGAM, PLEK) in pan-cancer." (PMID 40895569, 2025). "We also observed significantly decreased levels of GLUT4, GCK, CD36 and CPT1b for most of the UCP1-CRISPRa co-cultured cancer organoids, suggesting that they have lower glycolysis and fatty acid metabolism." (PMID 39905264, 2025).
cancer (continued). "Collectively, aberrant lipid metabolism is a key driver of MDSC-mediated immunosuppression, and metabolic targets such as CD36, FATP2, COX-2, β2-AR, and LOX-1 represent promising strategies for cancer therapy." (PMID 41312365, 2025). "Research has demonstrated that established FA protein transporters present in the plasma membrane, such as CD36 (FA translocator), SLC27 (FA transporter family), and FABPs (plasma membrane FA binding proteins), among others, exhibit up-regulation in cancer." (PMID 41034734, 2025). "Targeting CD36, FASN, SREBP, or cholesterol-regulatory pathways thus holds promise for attenuating Treg-mediated suppression and improving the efficacy of cancer immunotherapy." (PMID 41312365, 2025). "Studies have found that many of the key mediators of FAO, such as CD36, CPT1 (including CPT1A, CPT1B and CPT1C) and CPT2, are overexpressed in a variety of malignant tumors, and FAO has been found to be enhanced in a variety of cancers." (PMID 40514365, 2025). "To assess the significance of CD36 in fatty acid transportation, we generated HCT116 cells with stable CD36 knockdown and subsequently incubated them with adipocyte CM pretreated with MIIP+/− cancer cell CM." (PMID 38245780, 2024). "Although it has been reported that [123I]BMIPP uptake in the myocardium is mediated by CD36, [123I]BMIPP is primarily transported into cancer cells by CD36 and FATP, which is newly evident in cancer." (PMID 39062992, 2024). "Regarding the microenvironment, both CD36 and MYD88 showed a significant positive correlation with stromal score, immune score and overall microenvironment score in various cancers." (PMID 38742843, 2024). "CD36 antagonist, Nobiletin (NOB) and its derivatives, including 5-Demethylnobiletin (5-DMN) and NOB-metabolites, show an anti-cancer effect by regulation of cell cycle, apoptosis, and inflammation in CRC cell lines." (PMID 39125923, 2024). "Both results illustrate the intricate regulatory networks that include CD36 and NDRG2, as well as their roles in regulating metabolic pathways and safeguarding against cancer." (PMID 38747892, 2024). "A newly study demonstrates that CD36 palmitoylation promotes MUFA-specific uptake and protects cancer cells from palmitate-induced toxicity." (PMID 39551780, 2024). "The pharmacological inhibition of CD36 by SSO has also been used in several pre-clinical studies in mice and rats for the treatment of cancer and cardiovascular diseases." (PMID 37371076, 2023). "CSPG4, CD36, CD44 and GD2 were already shown to be involved in cancer cell migration and/or proliferation." (PMID 37803478, 2023). "QUE alone largely downregulated some genes with a role in promoting cancer (e.g., OLFML2B, EMILIN2, and CD36), which is consistent with the anticancer potential of this natural extract." (PMID 37755981, 2023). "Compared with the adjacent normal tissues and cancer tissues of patients taking atorvastatin, the expressions of MMP9, MMP12, CD36, and FABP4 in LUSC tissues increased significantly." (PMID 37978381, 2023). "Notably, because many of these metabolic disorders often present as co-morbidities in cancer patients, it is feasible that anti-CD36 therapy could also have the potential to simultaneously treat those disorders, adding even further therapeutic value for this emerging class of inhibitors." (PMID 37371076, 2023). "Our data further showed that CD36+ CAF-derived MIF promotes immunosuppressive TME and cancer stemness by enhancing MDSC expansion and suppressing T-cell-mediated antitumor immunity." (PMID 36878933, 2023). "Experimental studies in mice have shown that the CD36-neutralizing antibodies FA6.152 and JC63.1 hold promise for inhibiting cancer cell metastasis in various cancer types." (PMID 37545500, 2023). "However, transcription factors responsible for CD36 upregulation in cancer are largely unknown." (PMID 37371076, 2023).
cancer (continued). "The cancer cells disseminated in these white adipose tissues express FASN, which is a marker of lipid metabolism, and CD36, which is a transporter of extrinsic fatty acids." (PMID 36434071, 2022). "The co-occurrence of DGAT1 amplification with FASN, CD36, or MAGL amplification in human cancers was significant, arguing for these co-aberrations being synergistic, in keeping with DGAT1 facilitating safe accumulation of FA in cancer cells." (PMID 35732120, 2022). "It is also worth mentioning that recently several papers have uncovered the crucial roles of CD36 and FABP5 in intratumoral T cells, expediting our understanding of fatty acid uptake and cancer immunosurveillance." (PMID 39872079, 2022). "For example, the CD36-mediated bad cholesterol uptake in CD8+ T lymphocytes can lead to their dysfunction and cancer progression." (PMID 35790992, 2022). "Most of these processes are mediated by CD36, low-density lipoprotein receptor, and FABP in the cancer cell membrane, which are potential therapeutic targets for cancer." (PMID 35216285, 2022). "Cancer cells utilize secreted lipases like lipoprotein lipase (LPL) to hydrolyze FA from triglycerides, and FA transporter proteins (FATP) like CD36 and SLC27 family members and FA-binding proteins (FABP) to facilitate uptake." (PMID 35732120, 2022). "Other studies have emphasized the critical role of CD36 in promoting the cellular proliferation, progression, and metastasis of primary CRC and other cancers." (PMID 36556492, 2022). "CD36, PDK4, and THBS1 were highly expressed in cancer tissues, and G3BP2, PTPRB, and TMEM125 were lowly expressed in cancer tissues." (PMID 36147333, 2022). "Although CD36, SREBPs, PD-L1/2, FABP5, CPT-1, ACC1, GLUT1, and FAS has shown promising prospects to be potential metabolic drug targets of cancer, their context-dependence and varied implications in T-cell subtypes urge for more research." (PMID 36203151, 2022). "CD36, THBS1, and PDK4 were highly expressed in cancer tissues, whereas PTPRB, G3BP2, and TMEM125 were lowly expressed in cancer tissues." (PMID 36147333, 2022). "When oxLDL upregulated CD36 in HNC cell lines, the migration of cancer cells were reduced after oxLDL exposure." (PMID 36185215, 2022). "Recent studies of our group demonstrated the role of adipocyte and endothelial CD36 in LCFA mobilization from WAT and their bioavailability for cancer cells." (PMID 35991116, 2022). "Studies have identified CD36 expression as a driver of EMT in cervical, ovarian, colon, breast, hepatocellular carcinoma, and pancreatic cancers." (PMID 35991116, 2022). "The direct importance of CD36 interaction with PHB1/and ANX2 in cancer cells remains to be established." (PMID 35991116, 2022). "And these AML cells can fully utilize fatty acid oxidation to activate cancer-promoting signaling pathways such as AMPK, and up-regulate genes such as PPARγ, FABP4, CD36 and BCL2 genes to promote their own survival and proliferation." (PMID 36002858, 2022). "Our results showed overexpression of CD36 in the hepatocytes of replacement CRCLM lesions; specifically, those bordering the cancer cells." (PMID 34376784, 2021). "Based on the observation that CD36 mediated fatty acid mobilization from adipocytes, we investigated the importance of adipocytic CD36 in LCFA transport to cancer cells." (PMID 34314388, 2021). "IL-6 delivers signals through the STAT3 pathway, and recent studies have reported that CD36 is a downstream target of activated STAT3, suggesting that upregulation of IL-6 expression would further increase the uptake of FAs by cancer cells." (PMID 34722305, 2021). "Cancer cells uptake lipids through a variety of routes, including CD36/fatty acid translocase, low-density lipoprotein (LDL) mediated endocytosis, and fatty acid transport proteins." (PMID 34603046, 2021). "However, whether CD36 reprograms glucose metabolism of cancer cells is largely unknown." (PMID 33771982, 2021).
cancer (continued). "Our observation of a correlation between CD36 and FABP4 in a variety of cancers, and the direct interaction between CD36 and FABP4 offer a key insight to how adipocyte induce metabolic reprogramming." (PMID 34561446, 2021). "CD36, also known as fatty acid translocase (FAT), is responsible for maintaining lipid homeostasis, angiogenesis and metastasis in cancer cells." (PMID 33916349, 2021). "ER+ BC cells grown in coculture with DLL4+-HMVECs had higher levels of gene expression of cancer stemness-related genes (CD44, ALDH1A1, KLF4, and CD36) and PKD-1, as compared to ER+ BC cells grown in monoculture." (PMID 34168243, 2021). "Uptake and use of external FAs are particularly relevant for certain cancer types, including ovarian, colorectal, breast and mutant KRAS lung cancer, while FA translocase CD36 has been demonstrated to play a key role in metastasis." (PMID 34203535, 2021). "The interaction between CD36 and TGF-β stimulates EMT mechanisms to enhance the migration and metastasis of cancer cells." (PMID 32380783, 2020). "Therefore, CD36 may be a potential target for cancer treatment." (PMID 31847240, 2019). "Apoptotic cancer cells expose oxidized LDL-like sites on their surface that can be recognized by macrophage scavenger receptors such as SRA, LOX1, and CD36." (PMID 31766495, 2019). "An integrated analysis focused on lipid metabolism and local immune response indicated HMGGCS2, CD36, and GPX2 as differential hub genes of lipid metabolism in the pan-cancer immune microenvironment." (PMID 31493764, 2019). "Together, our findings highlight the potential application of CD36 inhibition for BTZ sensitization and suggest the use of FTIR spectroscopy as a promising technique in cancer research." (PMID 31022903, 2019). "For instance, in acute monocytic leukemia, bone marrow adipocytes can promote the expression of CD36 and AMPK genes in cancer cells, which increases FAO and mediates the survival and development of cancer cells." (PMID 31410189, 2019). "Therefore, targeting CD36 could represent a potential immunotherapeutic strategy for cancer." (PMID 31410189, 2019). "Several membranous receptors, including CD36, integrin α4β1, and integrin αVβ3, have been shown to mediate the TSP-2’s physiological roles on cancers." (PMID 28122633, 2017). "Nevertheless, some putative side-effects of using TAX2 as an anti-cancer agent still need to be explored, particularly as TSP-1 interaction with CD47 and/or CD36 is also known to modulate platelet aggregation." (PMID 26578962, 2015). "Cells with mesenchymal-like morphology deriving from normal and cancer tissues showed similar levels of CD14, CD29, CD36, CD44, CD45, CD49e, CD73, CDw90, CK18, FLT-1, STRO-1, SH4, HLA-ABC, and integrin α2β1 expression." (PMID 22330345, 2012). "Furthermore, CD36 enrichment in TGF-β-dominant and inflammatory immune subtypes, along with its correlation with multiple steps of the cancer immunity cycle, strengthens its proposed role in shaping immune infiltration patterns." (PMID 41550652, 2025). "TIPE2 was stained in the cytoplasm and nucleus of cancer cells, while CD36 was stained in the membrane with or without cytoplasmic expression of cancer cells." (PMID 40060230, 2025). "Moreover, cancer cells co-cultured with CRISPRa-modified adipocytes exhibited decreased FA uptake and reduced expression of FAO-related genes such as CD36 and CPT1B." (PMID 41345744, 2025). "CD36, also known as fatty acid translocase, plays a role in WAT lipolysis by triggering the mobilization of LCFA from adipocytes and therefore increasing the availability of FFAs for cancer cells in the TME." (PMID 39496581, 2025).